ALB (albumin)
Diseases named in the same sentence as ALB in open-access papers (continued):
Sharing a sentence is not in itself a finding about the gene and the disease.
diabetic nephropathy (continued). "Then, the albumin/creatinine ratio (ACR), Estimated Glomerular Filtration Rate (e GFR), routine urine examination, and diabetic profile, including HbA1c, were evaluated to confirm Diabetic Nephropathy." (PMID 39626591, 2024). "In our study, there was a negative correlation between serum albumin levels and overall mortality in diabetic kidney disease patients." (PMID 38600468, 2024). "Moreover, oral consumption of ZnCM not only significantly reduced the urinary volume and urine albumin but also remarkably decreased the levels of serum BUN, creatinine, urea, and uric acid in Cd-exposed rats with diabetic nephropathy induced by STZ." (PMID 38903987, 2024). "The mean albumin level of the diabetic nephropathy group was 4.6 ± 0.4 g/dL and the albumin of non-nephropathic subjects was 4.7 ± 0.4 g/dL (p = 0.58)." (PMID 37510145, 2023). "This particular form of DKD is called nonproteinuric diabetic kidney disease and is defined by an eGFR < 60 mL/min/1.73 m2 and a urine albumin to creatinine ratio (Ua:CR) ≤ 300 mg/g creatinine." (PMID 35896816, 2023). "The urinary albumin-to-creatinine ratio (UACR) and estimated glomerular filtration rate (eGFR) are commonly used as screening parameters and clinical staging criteria for diabetic nephropathy, a microvascular complication of DM." (PMID 36632822, 2023). "More importantly, treatment of diabetic kidney disease in uninephrectomized db/db mice with a selective CTSS inhibitor (RO5461111) improved endothelial injury, albuminuria, and glomerulosclerosis as well as albumin leakage in the retina." (PMID 36059966, 2022). "Third, data on some important variables that can influence diabetic nephropathy, such as smoking history, albumin, C-Reactive protein, and CKD etiology, were lacking." (PMID 34461808, 2021). "The low Na–Cl concentration was associated with the composite outcome after covariate adjustments (age, sex, DM, diabetic nephropathy, CVD, ACEIs/ARBs, loop diuretics, cigarette smoking, BMI, serum albumin, SBP, UACR, Hb, and CKD stages; HR 1.384; 95% confidence interval [CI], 1.116–1.717)." (PMID 30168046, 2019). "WT-mice fed a HFD exhibited an elevated albumin-to-creatinine ratio (ACR) and decreased creatinine clearance compared to chow-fed WT-mice, suggesting the development of proteinuria (a marker of diabetic nephropathy) and renal dysfunction." (PMID 30972066, 2019). "RAS inhibitor exerted protective effect on the progression of urinary albumin excretion in subjects with type 2 diabetes without diabetic nephropathy." (PMID 30525055, 2018). "Current diagnosis of diabetic kidney disease is based on the presence of reduced estimated glomerular filtration rate and/or an increased urinary albumin excretion in absence of other renal disease." (PMID 29910771, 2018). "This not only underscores the relevance of this finding but also allows to hypothesize a potential pathophysiologic link between suPAR, urinary albumin excretion and progression to CKD in diabetic nephropathy, which has to be addressed in future trials." (PMID 28091558, 2017). "Diabetic tubulopathy is an emerging entity that explains the occurrence of albuminuria in the early stages of diabetic nephropathy as a result of the impaired tubular reabsorption of albumin, rather than of its increased glomerular filtration." (PMID 27841047, 2017). "Diabetic nephropathy (DN), which is defined as increased urinary albumin excretion in the absence of other renal diseases, has emerged as a leading cause of CKD globally." (PMID 28744310, 2017). "Plasma sRAGE correlates positively with albumin excretion in T2DM patients, which may represent an early marker of diabetic nephropathy." (PMID 26357663, 2015). "Increased urinary albumin excretion is not simply an aftermath of glomerular injury, but is also involved in the progression of diabetic nephropathy (DN)." (PMID 26398934, 2015).
diabetic nephropathy (continued). "In preclinical studies, researchers constructed Arginine-Glycine-Aspartic acid-Human Serum Albumin-Tacrolimus (RGD-HSA-TAC) nanoparticles to target the delivery of tacrolimus to podocytes, which resulted in a reduction of podocyte injury and albuminuria in mice with diabetic kidney disease." (PMID 40534883, 2025). "Therefore, a more sensitive and specific marker for diabetic nephropathy, rather than urinary albumin excretion, is needed." (PMID 40003909, 2025). "Early detection and staging of diabetic nephropathy are impossible without urinary albumin levels." (PMID 39031296, 2024). "Colchicine was studied in a randomized controlled double-blind clinical trial in diabetic nephropathy where colchicine decreased neutrophil-related chronic inflammation; however, it did not lower creatinine, urinary albumin/creatinine ratio and did not prevent overt nephropathy either." (PMID 37744367, 2023). "On the other hand, the median weight, waist circumference, BMI, blood Hb and Htc, blood platelet count, serum albumin, C-reactive protein, HbA1c, fasting glucose, eGFR, and serum lipids of the patients, with and without diabetic nephropathy, were significantly different (p < 0.05 for all)." (PMID 37762893, 2023). "Similarly, significantly decreased levels of serum albumin were reported in diabetic nephropathy subjects compared to the diabetic patients without diabetic nephropathy." (PMID 37762893, 2023). "Serum creatine (SCR), blood urea nitrogen (BUN) and urinary albumin excretion rate (UAE) were usually selected as indicators of renal function and thus were included in the meta‐analysis to explore the relationship between different modeling methods and renal function in diabetic nephropathy." (PMID 37723622, 2023). "For example, kakonein could lower the levels of urinary albumin excretion, serum creatinine (CRE) and blood urea nitrogen (BUN), meanwhile upregulated the heparan sulphate proteoglycan expression and creatinine clearance rate diabetic nephropathy." (PMID 34180143, 2021). "In summary, the study showed that oral carnosine supplementation could reduce urinary TGF-β level in T2DM with diabetic nephropathy, but without significant effects on urine albumin, indicating an additional renoprotective effect from conventional therapy." (PMID 34174842, 2021). "Results of some studies showed that diabetic tubulopathy is an emerging entity that explains the occurrence of albuminuria in the early stages of diabetic nephropathy as a result of the impaired tubular reabsorption of albumin, rather than of its increased glomerular filtration." (PMID 31281843, 2019). "Since diabetic nephropathy was strongly associated with Nε-CML and not albumin-based AGE, the pathogenesis of diabetic nephropathy may be predominantly related to lipid peroxidation, rather the protein glycation." (PMID 30227659, 2018). "Moreover, the urinary albumin-to-creatinine ratio (ACR), common clinical indicator to assess the severity of diabetic nephropathy, in the db/db control mice increased compared to that in the normal mice and S. suberectus extract treatment markedly reversed this change." (PMID 30223524, 2018). "Albuminuria is often present in patients with diabetic kidney disease but there is also a subset of patients who develop diabetic kidney disease, as determined by declining glomerular filtration rate, without the presence of an elevated albumin excretion rate." (PMID 29910771, 2018). "While urinary albumin excretion measurement, a functional measure, remains the favoured method for identifying and monitoring persons who develop diabetic nephropathy, it is clear that not all individuals develop albuminuria or proteinuria before progressing to end-stage renal disease." (PMID 29396691, 2018).
diabetic nephropathy (continued). "However, albuminuria lacks specificity for diagnosing disease progression when the urinary albumin excretion is <300 mg/24 h and also lacks sensitivity since diabetic nephropathy can frequently progress without an increase in albumin excretion." (PMID 28577020, 2017). "Furthermore, compared with nephrosclerosis, diabetic nephropathy was characterized at RRT initiation by higher BMI, higher systolic and diastolic BPs, and higher CRP, NT-proBNP, and albuminuria levels as well as lower age and serum albumin levels." (PMID 26839894, 2016). "Angiotensin-converting enzyme inhibitors (ACEIs) and angiotensin-II receptor blockers (ARBs) are often administered to both diabetic and non-diabetic nephropathy patients, and are established as recommended treatment agents for non-diabetic nephropathy patients with albumin excretion." (PMID 26475266, 2015). "Reductions in rate of urinary albumin change, urinary NAG, and maintained podocyte numbers, with parallel improvements in oxidative damage and chronic inflammation, might be related to beneficial effects of exercise in diabetic kidney disease." (PMID 22899901, 2012). "However, a fractional micropuncture study demonstrated the proximal tubular albumin reabsorption to decrease without an increase in the glomerular albumin filtration in the early stages of streptozotocin-induced diabetic nephropathy." (PMID 22685655, 2012). "Compared to the diabetic NOD mouse, which displays characteristics of early human diabetic nephropathy, the diabetic OVE26 transgenic mouse, displays characteristics significantly closer to advanced human diabetic nephropathy, which include notably a dramatic increase of urinary albumin excretion." (PMID 16371158, 2005). "Similarly, early detection of diabetic nephropathy may be limited by lack of routine testing for urine albumin." (PMID 40313465, 2025). "Multiple studies have determined that not all patients with diabetic kidney disease exhibit elevated urinary albumin-creatinine ratio values in the early stages of the condition, suggesting that it may not be sufficiently sensitive as a marker during the initial phases." (PMID 39125705, 2024). "While the low-density lipoprotein/albumin ratio did not exhibit a significant correlation in our study, it is essential to note that dyslipidemia, particularly elevated LDL levels, remains an important risk factor for the development and progression of diabetic nephropathy." (PMID 37791152, 2023). "This was observed despite there being no functional differences in albumin excretion between the intervention (renin–angiotensin system blockade) and placebo groups, thus highlighting the relevance of the retinal microvasculature as an early biomarker of diabetic nephropathy." (PMID 29396691, 2018). "In diabetic patients with more than 5 years of hyperglycemia, appearance of persistent albuminuria [albumin excretion rate (AER) > 300 mg/24 h] without any urinary tract infection (UTI), other renal diseases or heart diseases represents diabetic nephropathy." (PMID 24936198, 2014). "Second, 274 (30.5%) of the total patients lacked urine albumin-to-creatinine ratio (UACR), which may strongly influence our diabetic nephropathy classification." (PMID 38351110, 2024). "However, gender, BMI, laboratory test results (levels of Hb and ALB, WBC, and lipid profile) and the incidence of diabetic nephropathy were not significantly different between the two groups." (PMID 32414389, 2020). "Diabetic kidney disease (DKD) is thought to result from a progression of systemic and local insults, clinically represented by impaired renal function with or without elevated urinary albumin excretion." (PMID 33584550, 2020). "Moreover, urinary albumin excretion and glomerular filtration rate (GFR) are also affected in non-diabetic renal disease, and accordingly not specific for diabetic nephropathy." (PMID 20975990, 2010).
diabetic nephropathy (continued). "However, in early-stage diabetic nephropathy, CML was not significantly correlated with the urinary albumin to creatinine ratio, indicating that CML might not be a reliable marker for early nephropathy." (PMID 40722744, 2025). "Patients were stratified into non-diabetic kidney disease (non-DKD), albuminuric diabetic kidney disease (ADKD), and NADKD groups according to their estimated glomerular filtration rate (eGFR), urinary albumin creatinine ratio (UACR), and urinary albumin excretion rate (UAER)." (PMID 40438382, 2025). "Moreover, women’s infection-related mortality risk was lower than that of men who were younger, with longer dialysis vintage, with non-diabetic nephropathy, no history of CVD, higher levels of blood hemoglobin, higher serum levels of creatinine or albumin, or lower levels of serum total cholesterol." (PMID 35013378, 2022).
Stroke (568 papers, 2005 to 2026). Sudden impairment of blood flow to a part of the brain due to occlusion or rupture of an artery to the brain. "Previous studies have generally indicated that low serum albumin levels are associated with poor prognosis in patients with stroke." (PMID 41432712, 2026). "This study found that LMR was the most informative biomarker for predicting stroke, while the strongest predictors of all-cause mortality were ALB, fibrinogen and LMR." (PMID 40073613, 2025). "Low serum albumin concentration has been proven to be linked with an elevated incidence and mortality of myocardial infarction, coronary heart disease, stroke, as well as with all-cause mortality, cardiovascular mortality, and cancer mortality." (PMID 40929100, 2025). "Reduced serum albumin levels demonstrate associations with ischemic heart disease, heart failure, atrial fibrillation, stroke, and venous thromboembolism." (PMID 41561116, 2025). "In contrast, multiple studies have investigated the urinary albumin-to-creatinine ratio (uACR) with stroke risk and intracranial atherosclerosis." (PMID 40917659, 2025). "Studies have shown that lower serum albumin levels in stroke patients are associated with poorer outcomes." (PMID 39957766, 2025). "A 2021 retrospective study found that NPAR outperformed other biomarkers, such as albumin and neutrophil-to-leukocyte ratios, in predicting stroke-associated pneumoni." (PMID 39935611, 2025). "In patients with stroke, albumin levels are inversely associated with stroke severity, degree of disability, and functional outcomes." (PMID 40821648, 2025). "Compared with the SIRI and SII indices, the CALLY index exhibits greater stability and accuracy in predicting stroke risk, potentially due to its dependence on serum albumin levels." (PMID 40242622, 2025). "For example, albumin levels less than 4.1 g/dL were associated with a higher risk of perioperative stroke." (PMID 40106818, 2025). "Reduced serum albumin levels have been linked to ischemic heart disease, heart failure, atrial fibrillation, stroke, PAD, and venous thromboembolism, and are an independent risk factor." (PMID 40041168, 2025). "Low serum albumin levels are epidemiologically linked to incident ischemic heart disease, heart failure, atrial fibrillation, stroke, and venous thromboembolism, indicating its potential in indicating lactate metabolic dysfunction and disease prognosis." (PMID 40821648, 2025). "Declining glomerular filtration rate (GFR) and elevated urinary albumin are associated with increased stroke risk." (PMID 41368362, 2025). "The serum albumin-to-globulin ratio (A/G ratio) is strongly associated with the occurrence and prognosis of stroke." (PMID 40070476, 2025). "Prior studies have focused mainly on the urinary albumin-to-creatinine ratio (uACR) with cerebral atherosclerosis and stroke risk." (PMID 40917659, 2025). "For instance, the EACH score identifies an albumin level of 4.1 to 4.4 mg/dL as being associated with the lowest perioperative stroke risk." (PMID 40106818, 2025). "A meta-analysis found that the risk of ischemic heart disease, myocardial infarction, any stroke, and ischemic stroke increased by 1.17-fold, 1.25-fold, 1.37-fold, and 1.46-fold, respectively, for every 10 g/L reduction in plasma albumin." (PMID 40438231, 2025). "Empirical evidence from prior studies has indicated that elevated creatinine or diminished albumin levels are individually linked to an unfavorable prognosis in stroke patients." (PMID 41170336, 2025). "While ALB showed a robust protective impact in hypertensive people, with greater ALB levels linked to a decreased risk of stroke (OR 0.50, 95% CI 0.37–0.68), we also discovered a positive correlation between CRP and stroke risk (OR 1.13, 95% CI 1.04–1.22)." (PMID 40491586, 2025). "This study found that LMR was the most informative biomarker for predicting stroke, while the strongest predictors for all-cause mortality were ALB, fibrinogen and LMR." (PMID 40073613, 2025).